FMR1 (fragile X messenger ribonucleoprotein 1)
Diseases named in the same sentence as FMR1 in open-access papers (continued):
Sharing a sentence is not in itself a finding about the gene and the disease.
Anxiety (continued). "Fmr1 KO mice with transgenic expression of the human FMR1 gene have demonstrated reduced anxiety and increased exploratory behavior in addition to the correction of some KO behavior phenotypes." (PMID 28894415, 2017). "Acamprosate treatment modified behavior in anxiety and locomotor tests in Fmr1 KO mice in which control-treated KO mice were shown to deviate from control-treated WT mice." (PMID 28616095, 2017). "Decreased anxiety-like behavior and hyperactivity in the open field in Fmr1 KO mice are very often observed but not always." (PMID 28451631, 2017). "Overall results for both EPM and open field tests indicate that the Fmr1 KO mice displayed decreased anxiety compared with controls, as previously reported in the inactive phase." (PMID 27294193, 2016). "We found a statistically significant main effect of genotype indicating that Fmr1 KO mice moved more in the center of the field, suggesting reduced general anxiety levels." (PMID 27294193, 2016). "We found that, in the active phase, Fmr1 KO mice have the same phenotype as reported in the inactive phase in open field activity, anxiety, and learning and memory." (PMID 27294193, 2016). "We found that in the active phase of the circadian cycle, Fmr1 KO mice are hyperactive, and demonstrate reduced anxiety and impaired learning and memory." (PMID 27294193, 2016). "We observed that fluoxetine reduced the latency of Fmr1 KO and wild-type mice to enter the center area in the open field test indicating reduced anxiety in both mouse groups." (PMID 24904293, 2014). "Young adult KINIH mice had a very similar behavioral phenotype to Fmr1 KO mice, with hyperactivity, reduced anxiety, impaired social interactions, and deficits on passive avoidance test of learning and memory." (PMID 25290064, 2014). "Elevated plus mazes are a common test for anxiety in mice, but show variable results in Fmr1 KO mice." (PMID 24550778, 2014). "When minocycline was administered to Fmr1-knockout mice, their hippocampal neurons exhibited mature dendritic spines, and, behaviourally, they showed decreased anxiety and improved exploration skills." (PMID 25187257, 2014). "Some studies report that Fmr1 KO mice show increased anxiety-related activity during social interaction, whereas other studies show decreased anxiety in open field studies." (PMID 24570656, 2014). "The reduced level of interactions of Fmr1 KO mice during the direct social interaction test, is therefore most probably due to social anxiety induced by the direct contact with the stimulus mouse." (PMID 25079250, 2014). "We found that fluoxetine reduced anxiety-like behavior of both wild-type and Fmr1 KO mice seen as shortened latency to enter the center area in the open field test." (PMID 24904293, 2014). "An acute treatment with BMS-204352 was therefore able to rescue the social deficits of Fmr1 KO mice by increasing affiliative behaviors, decreasing social anxiety and enhancing social recognition." (PMID 25079250, 2014). "Recent studies have shown that genetic reduction of STEP improves cognition, synaptic plasticity, and NMDA receptor subunit expression in mouse models of Alzheimer’s disease and reduced seizures, anti-social, and anxiety-related behaviors in Fmr1 KO mice." (PMID 23803181, 2013). "In Fmr1-KO mice, hyperactivity and increased time spent in the center of the OF arena often co-occur, the latter parameter indicating decreased anxiety." (PMID 24312033, 2013). "Compared with wild-type fish, fmr1 KO fish had reduced anxiety-related responses in the light/dark test." (PMID 23536755, 2013). "For example, fmr1 knockout (KO) mice were characterized as having several behavioral profiles similar to those of fragile X patients, including hyperactivity, reduced anxiety-related behavior, and learning and memory deficits." (PMID 23536755, 2013).
Anxiety (continued). "Furthermore, the use of the drug JZL184 (which inhibits the breakdown of 2-AG by MAGL) to enhance 2-AG signaling corrected hyperactivity and anxiety in Fmr1-KO mice." (PMID 38744725, 2024). "Fmr1 KO mice have previously been found to express increased anxiety-like behavior." (PMID 39335388, 2024). "In a study, a single injection of the FAAH blocker URB597 improved unpleasant memory and anxiety-like behavior in Fmr1-deficient mice without impairing their social behavior." (PMID 38744725, 2024). "However, restoration of FMRP to neurons in 6-week-old Fmr1 KO mice only had modest effects in anxiety-like behaviors and learning and memory paradigms relative to empty-vector treated mice." (PMID 39768191, 2024). "The poor nest building and the increased “approach” behavior (or reduced anxiety-like behavior) exhibited by the Fmr1 KO mice in the elevated plus maze assay could have common origins." (PMID 39308631, 2024). "Furthermore, treatment with the CB2 receptor agonist AM630 has shown to ameliorate anxiety and audiogenic seizure behaviors in the Fmr1 knockout mouse model." (PMID 38744725, 2024). "The specific contributions of motivation, reward, and anxiety-arousal to nest building are difficult to distinguish and the contribution of each to the overall deficit in nest building in the Fmr1 KO mouse is difficult to establish using the nest building assay alone." (PMID 39308631, 2024). "Although hyperactivity might influence the results of anxiety analyses, evaluation of Fmr1-KO mice in the EPM and open field test definitively demonstrates that these animals have a reduced anxiety." (PMID 37065917, 2023). "However, in the open-field test, constitutive Fmr1 KO mice tend to spend more time in the center of the box, indicative of a decrease in anxiety." (PMID 36692473, 2023). "Moreover, low anxiety in Fmr1-KO mice was validated by the longer time animals spent in the center of the open field box compared to B6 mice (p = 0.03)." (PMID 37065917, 2023). "In the C57 background, AEA improved cognitive impairments and anxiety phenotypes in Fmr1 KOs." (PMID 37671673, 2023). "Interestingly, Fmr1 KO mouse models have frequently shown decreased anxiety (more time in open/light space), compared to wild type littermates, in these kinds of anxiety tests, which is contrary to human findings." (PMID 35075104, 2022). "To evaluate whether the hyperactivity displayed by Fmr1-Δexon 8 rats could be related to changes in anxiety-like behaviors, we also performed the elevated plus maze test." (PMID 36581671, 2022). "The time spent in central area and the ratio of total distance travelled in the central area were significantly increased in Fmr1 KO mice, suggesting that Fmr1 KO mice manifested reduced anxiety-like behavior compared with the WT mice, which was consistent with other reports." (PMID 35783275, 2022). "Many researchers observed a low level of anxiety in Fmr1 KO mice." (PMID 36470953, 2022). "Indeed, here we demonstrated that post-weaning exposure to this diet exaggerated the reduced anxiety characteristic of the Fmr1 knockout." (PMID 35089938, 2022). "In this study, CBD administration resulted in a further reduction in anxiety-like behavior in both Fmr1-deficient and WT mice, without any effect on locomotor activity, social, or cognitive performance." (PMID 35629320, 2022). "Importantly, increasing the bioavailability of 2-AG normalized plasticity deficits and rescued the hyperactive, anxiety, and cognitive impairments phenotypes of the Fmr1-KO mouse." (PMID 34440392, 2021). "JZL-184 treatment also ameliorated anxiety-like and hyperactivity phenotypes in Fmr1 KO mice." (PMID 34645383, 2021). "Next, we assessed whether JZL-184 treatment reduces anxiety-like behaviors and hyperactivity in Fmr1 KO mice." (PMID 34645383, 2021).
Anxiety (continued). "However the two studies are inconsistent with respect to fmr1 impact on anxiety where one study reports fmr1 mutants to have anxiolytic behavior, while the other reports increased anxiety like behavior." (PMID 33262688, 2020). "In the EPM test, Fmr1 KO mice also showed impaired anxiety-like behavior." (PMID 31882402, 2020). "Whereas this may have biased our results, the fact that Fmr1 KO/Fxr2 Het mice demonstrated the least anxiety-related behavior suggests that the direction of the bias would be to underestimate the genotype difference." (PMID 30654445, 2019). "Finally, arbaclofen, a GABAB agonist, improved protein synthesis, the abnormal auditory-evoked gamma oscillations, working memory and anxiety-related behavior in Fmr1 KO mouse." (PMID 31035599, 2019). "However, another measure of anxiety-like behavior, the zero maze, showed a statistical trend indicating that Fmr1 KO/Fxr2 Het mice had even lower anxiety than Fmr1 KO mice." (PMID 30654445, 2019). "Similarly, our open field results suggest that Fmr1 and Fmr1 KO/Fxr2 Het mice have similar reductions in anxiety compared to WT mice." (PMID 30654445, 2019). "In this study, we used a systemic Fmr1 knockout in order to investigate both genotype‐ and sex‐specific differences across multiple measures of sociability, repetitive behaviors, activity levels, anxiety, and fear‐related learning and memory." (PMID 29075560, 2017). "Although the current Fmr1 KO mouse anxiety data are difficult to interpret, taken together with previous reports in other rodent models and humans with FXS, acamprosate may have utility as an anxiolytic agent in FXS." (PMID 28616095, 2017). "As an additional measure of anxiety levels in Fmr1 KO mice, we determined behavior in the EPM." (PMID 27294193, 2016). "Fmr1 KO mice had a significantly increased percentage of time spent in the open arms compared with control mice (p < 0.001), also suggesting reduced general anxiety levels." (PMID 27294193, 2016). "Genetic reduction of STEP could attenuate audiogenic seizures, improve characteristic social abnormalities, and reverse anxiety-related behaviors in Fmr1 knockout mice, suggesting that STEP might be a therapeutic target for treating fragile X patients." (PMID 25767435, 2015). "In addition, chronic minocycline reduced anxiety-related behavior, improved cognitive function in young Fmr1 knockout mice, and reversed impaired social communication during mating among fragile X mice." (PMID 25767435, 2015). "We considered whether the increased anxiety-like behaviors exhibited by Fmr1 KO mice might contribute to their deficits in the gap cross assay." (PMID 25296296, 2014). "Neuronal release of BDNF can alter anxiety-like behaviors in mice and age-dependent changes in the expression of BDNF observed in the brain of Fmr1 KO mice could at least partially explain the alterations seen in the anxiety phenotype in different studies." (PMID 24904293, 2014). "fmr1 KO fish spent more time in the white compartment (p<0.01) and had greater numbers of midline crossings compared to wild-type fish (p<0.01), indicating lower anxiety and increased locomotion in KO fishes." (PMID 23536755, 2013). "Notably, FMR1 KO mice exhibit hyperactivity and also demonstrate decreased anxiety." (PMID 38534343, 2024). "These include hyperactivity, anxiety, deficits in spatial memory, alterations in social behaviors and ultrasonic communication; these behavioral alterations started to emerge in Fmr1 heterozygous females during the juvenile age and were mostly confirmed at adulthood." (PMID 37511156, 2023). "Hence, the lower anxiety-like behavior observed in Fmr1-KO mice detected by a higher frequency to enter and more time spent in the open arms of the EPM test could be affected by the higher activity and hyperactivity observed in these mice." (PMID 37065917, 2023).
Anxiety (continued). "Indeed, whereas we did not observe any genotype difference in Study 1, in accordance with previous studies by us and others, reduced anxiety-like behaviors of Fmr1-KO mice were detected in the elevated plus maze and open field test in Study 2, as previously reported as well." (PMID 37566006, 2023). "Given their genetic status as carriers of the FMR1 premutation or full mutation, biological mothers of children with FXS, on average, were expected to display elevated rates of mental health symptoms, especially depression and anxiety, and parenting stress relative to the general population." (PMID 34899411, 2021). "Finally, results from the SAT reinforced that the anxiety-related phenotype observed in Fmr1 KO2 mice could be normalized by gaboxadol treatment." (PMID 31293404, 2019). "It is possible that the observed increased time in open that is routinely observed in Fmr1 KO mice, here and by others, is the result of increased locomotor behavior rather than the result of anxiety or risk-taking behavior, although this finding is difficult to reconcile with the human condition." (PMID 28616095, 2017). "Unexpectedly, combinations of these 5-HT and DA compounds at low doses synergistically stimulate Ras-PI3K/PKB signal transduction and GluA1-dependent synaptic plasticity and remarkably restore normal learning in Fmr1 knockout mice without causing anxiety-related side effects." (PMID 26257650, 2015). "In summary, in Fmr1 KOs, modulation of AEA signaling largely mitigates impairments in social behaviors, altering 2-AG signaling and CB2R activity impacts anxiety, and modulating CB1R activity improves cognition." (PMID 37671673, 2023). "In the present study, we characterize BTBR and Fmr1-KO mice for their ASD-related behaviors by assessing locomotor activity, anxiety-like, and repetitive behaviors." (PMID 37065917, 2023). "Based on the observed results from the open field test, we aimed to further explore anxiety-like behavior by the widely used elevated plus maze (EPM) test in BTBR and Fmr1-KO mice at the age of 10 and 7 weeks, respectively." (PMID 37065917, 2023). "For example, anxiety behaviours, so often observed in FXS patients, have yielded mixed results in studies of Fmr1 KO mice." (PMID 35075104, 2022). "For example, compared with the WT mice, Fmr1 KO mice displayed hyperactivity and anxiety phenotype, however, the basal expression level of c-fos is decreased in OFC and mPFC of Fmr1 KO mice." (PMID 35869039, 2022). "We used the EZM assay to assess anxiety behavior in vehicle- and BAER-101-treated Fmr1 KO and WT mice during a 5-min test." (PMID 34093287, 2021). "The results from three anxiety tests, center distance in the OFT, light/dark box, and SAT, demonstrate a robust phenotype in the Fmr1 KO2 mouse that is reversed by treatment with gaboxadol." (PMID 31293404, 2019). "Elevated zero maze was used to assess anxiety behavior in control (SAL- and CaCl2-treated) and Acamp-treated Fmr1 KO and WT mice during a 5-min test." (PMID 28616095, 2017). "A genotype effect on the time spent in the closed arms was observed, consistent with the detected decrease in anxiety-like behavior in the Fmr1 KO mice, regardless of the treatment." (PMID 39604505, 2025). "Together, we conclude that AMN082 does not affect locomotion or anxiety behavior in WT or Fmr1 KO mice." (PMID 38374465, 2024). "In conclusion, our data suggests that activation of mGluR7 alleviates repetitive behavior without affecting locomotion, anxiety, or sociability in Fmr1 KO mice." (PMID 38374465, 2024). "Ibudilast QD displayed a subtle but significant amelioration of anxiety in Fmr1 KO mice; however, this reduction was not to levels observed for WT mice (P < 0.0001 versus WT vehicle)." (PMID 38226317, 2024). "Mice with PV Fmr1-lacking INs showed anxiety-like behavior, altered social behavior and dysregulated de novo protein synthesis." (PMID 37188005, 2023).
Anxiety (continued). "Furthermore, administration of mGluR5 antagonists in FMR1 knockout mice demonstrated a variety of benefits in this preclinical FXS model phenotype, including reduced seizures and anxiety-like behaviors." (PMID 36624400, 2023). "In Fmr1-KO mice, there were no improvements in hyperactivity, anxiety level, and communication detected after R-Baclofen treatment." (PMID 37065917, 2023). "Previous studies showed similar results to the current findings where the empty vector did not change the hyperactivity, and higher anxiety-like behavior was shown by less time in the center of the open field exhibited by the Fmr1 KO mice." (PMID 36833432, 2023). "Although not consistently described in Fmr1-KO mice, emotional alterations in the elevated plus maze were also evaluated in order to assess potential confounding differences in anxiety-like behavior induced by CBDV treatments." (PMID 37566006, 2023). "Chronic treatment of adult male Fmr1 KO mice (FVB-129 background) with melatonin (via I.P. injection) reduced overall activity in the open field, increased anxiety-like behavior on the elevated plus maze, and improved learning and memory on a contextual fear conditioning task." (PMID 35720683, 2022). "The results suggest that the reduced anxiety characteristic of the Fmr1 KO is not present when tested around PD90 in this model, unlike previous studies conducted at an earlier time points." (PMID 35089938, 2022). "Overall, Fmr1 KO mice regardless of condition or age demonstrated less anxiety-like behavior than WT." (PMID 35833085, 2022). "The results showed that Fmr1 KO2 mice were hyperactive, had abnormal anxiety-like behavior, were more irritable and aggressive, and had an increased frequency of repetitive behaviors compared to wild-type (WT) littermates, which are all behavioral deficits reminiscent of individuals with FXS." (PMID 31293404, 2019). "Genetic reduction of MDM2 in adult new neurons did not affect overall locomotor activity or anxiety in either WT or Fmr1 KO mice but rescued behavioral deficits of Fmr1 KO mice." (PMID 29950602, 2018). "We find that classical behavioral phenotypes; such as hyperactivity, reduced anxiety, and learning and memory impairments; reported in the Fmr1 KO mice are not influenced by circadian phase." (PMID 27294193, 2016). "We report that phase did not alter the Fmr1 KO phenotype in open field activity, anxiety, and learning and memory." (PMID 27294193, 2016). "In contrast, Fmr1 KO mice exhibited reduced non-social anxiety compared to WT mice in the elevated plus maze." (PMID 25079250, 2014). "Reduced non-social but increased social anxiety have been reported in Fmr1 KO mice but the anxiety phenotype of Fmr1 KO mice has not been consistent in all studies." (PMID 24904293, 2014). "Previous behavioral studies have demonstrated that fmr1 KO mice replicate many of the human behavioral features of FXS, including hyperactivity, learning deficits, impaired social interaction, and abnormal anxiety-related responses." (PMID 23536755, 2013). "Fmr1 knockout (KO) mice, which lack expression of the mouse homolog of FMRP, exhibit morphological abnormalities, learning and memory defects, and behavioral problems including attentional dysfunction, impulsivity, anxiety, and excessive grooming." (PMID 22087250, 2011). "Our study shows that both the Fmr1 mutation and exposure to MIA led to similar core autistic traits, including impaired social communication and interaction, and repetitive behaviors, but not to associated comorbidities, such as hyperactivity and anxiety." (PMID 39604505, 2025). "Our findings along with previous literature suggest that Fmr1 KO mice may not robustly replicate the anxiety phenotype commonly found in humans with FXS." (PMID 39335388, 2024). "Ibudilast BID showed no efficacy for reducing anxiety in Fmr1 KO mice." (PMID 38226317, 2024).